TLR2 (toll like receptor 2)
Diseases named in the same sentence as TLR2 in open-access papers (continued):
Sharing a sentence is not in itself a finding about the gene and the disease.
neurodegenerative disease (29 papers, 2012 to 2025). A disorder of the central nervous system characterized by gradual and progressive loss of neural tissue and neurologic function. "Many studies have reported an association between TLRs, especially TLR2, 4 and 9, and neurodegenerative diseases such as PD, AD and ALS." (PMID 33262983, 2020). "It is possible that inflammatory microglia 2 may be responsible for inducing immune responses in neurodegenerative diseases, as aggregate forms of tau and αSyn act as endogenous ligands for microglial TLR2 and cause neurotoxicity in a TLR2-dependent manner." (PMID 40307569, 2025). "Furthermore, we will discuss the pro- and anti-inflammatory properties of TLR2 and recent findings in prominent TLR2-associated infectious and neurodegenerative diseases." (PMID 37569837, 2023). "TLR2 is an innate immune receptor, but increasing evidence demonstrates its role in neurodegenerative diseases, including AD and PD18,82." (PMID 35396576, 2022). "While TLR2 plays an important role in the innate immune system, it has been demonstrated that TLR2 also plays an important role in the pathogenesis of neurodegenerative diseases, including AD and PD16–20." (PMID 35396576, 2022). "The development of neurodegenerative diseases is reported to be connected with increased expression and activation of TLR2." (PMID 35682568, 2022). "This was previously reported in different models studying Tlr2 expression of microglia during inflammation and neurodegenerative diseases." (PMID 33540859, 2021). "TLR2 is one of the most studied TLRs related to neurodegenerative diseases." (PMID 37433768, 2023). "The TLR2/4 pathway could be a mechanism-based therapeutic strategy for neurodegenerative disease such as PD." (PMID 35401198, 2022). "Targeting neuronal TLR2/4 pathway might be a mechanistic-based therapy for neurodegenerative disease, such as PD." (PMID 35401198, 2022). "Thus, regulating TLR2-mediated microglia/macrophage activation has been recommended as a key therapeutic tactic for treating neurodegenerative diseases." (PMID 35682568, 2022). "Our findings reveal that exposure to fatty acids may determine the response of microglia to subsequent inflammatory challenge by a TLR2-targetting stimulus, which may have a critical impact on neurodegenerative disease processes." (PMID 35079937, 2022). "TLR2 is one of the most well-studied TLRs in the context of neurodegenerative diseases." (PMID 33262983, 2020). "TLR2 is one of the most studied TLR in respect to neurodegenerative diseases." (PMID 30333729, 2018). "Thus, controlling TLR2-mediated microglia activation and neurotoxicity has been suggested as an important therapeutic approach to treating neurodegenerative diseases." (PMID 29731715, 2018). "Thus, TLR2/4-mediated IL-17A signaling is required in retinal vascular degeneration, indicating that targeting TLR2/4-mediated IL-17A signaling is a novel strategy to promote revascularization and treat degenerative diseases." (PMID 27297042, 2016). "Although toll-like receptors are known to recognize misfolded proteins and trigger stress responses in various neurodegenerative diseases, TLR2 has not been directly linked with the recognition of prion deposition." (PMID 23068602, 2012). "TLR2 could enhance macrophage receptor with collagenous structure (Marco)–induced neuroinflammation by acting on the scavenger receptors cysteine-reach (SRCR) domain of Marco, which also suggested that TLR2 could serve as a novel target for reducing neuroinflammation in neurodegenerative diseases." (PMID 35873459, 2022). "We also identified the potential role of TLR2 in SARS-CoV-2-induced neuroinflammation and its potential link to other neurodegenerative diseases." (PMID 39057755, 2024). "The expression levels of TLR2 and TLR4 were found to be upregulated in the brains of patients with AD and other neurodegenerative diseases such as PD." (PMID 39408923, 2024).
neurodegenerative disease (continued). "Thus TLR2/4-mediated IL-17A inflammatory signaling is involved in vessel degeneration and revascularization, indicating that modulation of the TLR2/4-IL-17A pathway may be a novel therapeutic strategy for degenerative diseases." (PMID 27297042, 2016). "In this study, we used TLR2 and TLR4 double knockout mice to investigate their role in vessel regression and degeneration, which is the vital pathological change in numerous degenerative diseases." (PMID 27297042, 2016). "Therefore, the induction of neuronal TLR2 susceptibility by the E protein of SARS-CoV-2 may lead to the deposition of abnormal protein in the cells, thereby affecting the disease onset and/or accelerating the disease progression of proteinopathy-associated neurodegenerative diseases." (PMID 35396576, 2022). "Indeed, screening of innate immune receptors in animal models of AD, PD/DLB, and ALS revealed upregulation of TLR2 and CD14 as a common feature in all neurodegenerative diseases and therefore likely part of a non-specific effector phase common to many neurodegenerative diseases." (PMID 35979366, 2022).
immune disorders (19 papers, 2011 to 2024). "Extracellular HMGB1 upregulates the expression of pro-inflammatory factors including IL-6, IL-1β, IL-12, and TNF-α through the activation of TLR2/4, causing cytokine storms, immune disorders, and severe apoptosis in the spleen, thymus, and bursa of Fabricius." (PMID 38474071, 2024). "HMGB1-induced immune disorder provokes inflammatory storms causing cell and organ damage via the TLR2/4-NF-κB signaling pathway." (PMID 36139393, 2022). "Increased susceptibility to skin S. aureus infection and defect in TLR2 signaling have been regarded as specific features reflecting the immune dysfunction in AD." (PMID 26682905, 2015). "This process of immune dysfunction following traumatic injury is dominated by the pattern recognition receptors TLR2, TLR4 and TLR9." (PMID 37108280, 2023). "The increased abundance of inflammation-related microbiota resulted in immune disorders and intestinal barrier dysfunction by upregulating TLR2/4/5 and promoting the release of IL-1β and TNF-α." (PMID 33329010, 2020). "Before the beginning of the study, many experimental results confirm TLR2 and TLR4 are implicated in the regulation of a variety of inflammatory and immune disorders." (PMID 29348888, 2017). "TLR2 signaling, mostly activated on APCs, has been considered essential for the inflammatory response and for immune disorders." (PMID 22025895, 2011). "Peripheral blood analysis in patients with GC revealed that toll-like receptor 2 expression in CD8+ T cells was downregulated, which might be associated with immune dysfunction through the suppression of the perforin–granzyme pathway." (PMID 36983614, 2023). "However, the alleviation of immune disorders by knocking down TLR2 or TLR4 alone remained unimpressive due to the HMGB1 preferential recognition effect of TLR2 and the compensation effect of TLR4." (PMID 36139393, 2022). "More importantly, TLR4 could be activated by HMGB1 to trigger immune disorders after TLR2 was silenced." (PMID 36139393, 2022). "In addition, our results showed that TLR2/4 activated by HMGB1 further activates the NF-κB pathway to produce immune disorders." (PMID 36139393, 2022). "Modulation of TLR2‐mediated signaling might therefore provide novel directions for intervention within a broad spectrum of immune diseases." (PMID 30184256, 2018). "TIPE2 improves the PHSML-mediated CD4+T cells dysfunction by regulating TLR2/TLR4 pathway, providing a new intervention target following hemorrhagic shock-induced immune dysfunction." (PMID 35572554, 2022). "Toll-like receptor 2 (TLR2) signaling is thought to be essential for the inflammatory response and for immune disorders." (PMID 22025895, 2011). "Our group found that in the absence of TLR2, MG could induce inflammation via TLR6 in DF-1 cells, or TLR4 could be activated by HMGB1 to trigger MG-induced immune disorders in avian macrophage cells." (PMID 37238096, 2023).
metabolic disorders (17 papers, 2012 to 2024). "Toll-like receptor 2 (TLR2) has been demonstrated to participate in the progression of some metabolic disorders due to its role as a pro-inflammatory trigger." (PMID 36829598, 2023). "In human monocytes, vitamin D suppresses the mRNA expression of Toll-like receptor 2 (Tlr-2) and Toll-like receptor 4 (Tlr-4) proteins, which are important regulators of metabolic inflammation during the development of metabolic disorders." (PMID 35859985, 2022). "Previous studies suggested that TLR2 is critical for diet-induced adiposity and metabolic disorders in a mouse model." (PMID 24064574, 2013). "A. muciniphila could promote 5-HT levels in the colons of mice via its outer membrane protein Amuc_1100 and TLR2 signalling pathway, thus improving gastrointestinal diseases and metabolic disorders." (PMID 36835655, 2023).
cardiovascular disease (14 papers, 2019 to 2025). "Apart from being implicated in immunity, numerous studies have reported that many TLRs, including TLR2, are involved in the pathogenesis of cardiovascular diseases and their risk factors." (PMID 32650372, 2020). "It restores intestinal barrier function through the immunomodulatory effect of cell membrane protein AMUC-1100 binding to toll-like receptor 2 reducing macrophage infiltration, proinflammatory cytokines, and chemokine expression, therefore reducing the risk of cardiovascular disease." (PMID 34366839, 2021). "Supporting a role for TLR2 in cardiovascular disease, TLR2 blockade promotes protective effects in endothelial cells in vivo and in vitro." (PMID 34527000, 2021). "TLR2, TLR3, and TLR4 are the TLRs that are predominately expressed in cardiomyocytes and play a large role in mediating inflammatory responses that are associated with cardiovascular disease." (PMID 37034342, 2023).
neurological disorders (12 papers, 2015 to 2025). "The finding that both homologous (zymosan) and heterologous (LPS, poly(I:C)) TLR ligands are capable of regulating TLR2 gene expression may have important implications in understanding the relative contributions of different TLRs in neurological disorders associated with neuroinflammation." (PMID 26714634, 2015). "Third, TLR2 exerted functions in biological processes or other neurological diseases via the neuroinflammation pathway." (PMID 35873459, 2022). "Studies suggest that TLR2 activation by these endogenous “danger signals” is involved in the development of neuroinflammatory responses in various neurological disorders." (PMID 25879213, 2015). "Thus, TLR2 has been suggested as an efficient target to regulate unwanted inflammatory responses in neurological disorders." (PMID 30470240, 2018). "However, much remains unknown about the relationship between T. gondii infection-induced neurological disorders and the function of TLR2 in the brain." (PMID 29136637, 2017). "Feeding TLR ligands to GF mice suggests that these microbial products are sufficient to decrease neurologic disease, and our results show that TLR4 exposure may play a more prominent role than TLR2 signaling in this process." (PMID 31309928, 2019). "Recent studies have shown that Toll-like receptor 2 (TLR2) is involved in the innate immune response in various neurological diseases, yet neither its role in ICH nor the mechanisms by which it functions have yet been elucidated." (PMID 25879213, 2015). "TLR2 is also involved in glial cell activation detected in non-infectious neurological disorders." (PMID 30470240, 2018). "While Toll-like receptor 2 (TLR2) reportedly plays important roles in protective immunity against the parasite, the relationship between neurological disorders induced by T. gondii infection and TLR2 function in the brain remains controversial with many unknowns." (PMID 29136637, 2017).
cardiac diseases (5 papers, 2016 to 2022). "TLR2 is a pattern recognition receptor, which is involved in the pathological process of various heart diseases." (PMID 36225554, 2022). "TLR2 activation has a key role in metabolic and cardiac diseases and its presence is required to trigger IL-1β production in different animal models." (PMID 27882934, 2016). "A growing number of papers have reported that TLR2 plays a key regulatory role in heart disease." (PMID 32394311, 2020). "Thus, modulation of TLR2 signaling may provide a future treatment option for cardiac diseases." (PMID 27109115, 2016). "TLR2 and TLR4 play a central role in the pathogenesis of diverse heart disorders." (PMID 35891270, 2022).
adenocarcinoma (4 papers, 2016 to 2021). A common cancer characterized by the presence of malignant glandular cells. "Once TLR2 signalling is initiated during BE and early-stage adenocarcinoma, the positive amplification of TLR2-mediated inflammation and TLR2 expression on macrophages contributes to their polarisation and activation during disease progression." (PMID 33922955, 2021). "The expression of TLR2 was slightly, but significantly increased from normal epithelium towards adenocarcinoma." (PMID 27008696, 2016). "Receptors, including RAGE, TLR2, and TLR4, may be upregulated in the adenocarcinoma or stroma cells." (PMID 33167343, 2020). "PAFr and TLR2 are known to interact with intact pneumococci and purified pneumococcal peptidoglycan-teichoic acid complex (cell wall [CW]) on human brain microvascular endothelial cells (HBMEC) and human adenocarcinoma lung epithelial cells (A549)." (PMID 28049146, 2017).
gastrointestinal disease (4 papers, 2020 to 2023). A disease that occurs in the gastrointestinal system, excluding the hepatobiliary system. "Of note, in recent years, the TLR2 rs3804099 polymorphism has been thoroughly investigated in association with Helicobacter pylori infection, another important pathogen in gastrointestinal disease." (PMID 34322122, 2021). "The percentage of TLR2+ classical monocytes was correlated with the VAS of gastrointestinal disease activity (Rho = 0.377, P = 0.033." (PMID 32164729, 2020). "Toll-like receptor 2 (TLR2) is a potential therapeutic target for gastrointestinal diseases, in which TJ-related intestinal epithelial barrier disruption might be the main feature." (PMID 36360148, 2022). "A therapeutic strategy targeting TLRs to improve host immunity has been utilized to treat gastrointestinal disease by applying Lactobacillus species; for example, Lactobacillus crispatus can modulate epithelial cell defense against Candida albicans through the TLR2 and TLR4 pathways." (PMID 34322122, 2021).
hematologic malignancies (4 papers, 2017 to 2025). "Up to now, TLR2 inhibition in human patients has been tested in some clinical trials for the treatment of hematologic malignancies, using either monoclonal antibodies or small molecule inhibitors." (PMID 33321934, 2020). "Neoplastic cells from several hematological malignancies express TLR2, as their normal cell of origin did, and exploit its signaling pathway to promote their proliferation." (PMID 33321934, 2020). "The rs5743551 (−7202G>A) variation in the TLR1 gene, the rs7656411 (22215G>T) variation in the TLR2 gene and the rs11536889 (+3725G>C) variation in the TLR4 gene were genotyped in 365 recipients with hematologic malignancies and their unrelated donors in the discovery cohort." (PMID 28484092, 2017).
intestinal disease (4 papers, 2012 to 2024). "By detecting the presence of peptidoglycan and lipoteichoic acid, it has been shown that Toll-like receptor 2 (TLR2) plays a crucial role in the innate immune response to bacteria that are responsible for causing intestinal disease." (PMID 39034396, 2024). "Moreover, as in the case of other animal intestinal diseases, the protective role of PSA against CRC pathogenesis was also mediated by TLR2." (PMID 30065713, 2018).
benign tumours (2 papers, 2018 to 2019). "TLR4 and TLR2 were identified as dynamic in mediating the inflammatory response in the ischemic heart." (PMID 31109132, 2019). "Important upstream regulators in our study, unique to benign tumours were AREG, TLR2, TGF1B, HGF, MAP3K1." (PMID 30517191, 2018).
peripheral neuropathy (2 papers, 2021 to 2022). A disorder affecting the peripheral nervous system. "Further analysis confirmed that toll-like receptors (TLRs) were implicated with PD peripheral neuropathy, in which TLR2 exhibits the predominant expression." (PMID 34642321, 2021). "Secondly, TLR2 knockout mice or TLR2 siRNA treated mice will provide more conclusive evidence to validate the target role of TLR2 in PD peripheral neuropathy." (PMID 34642321, 2021). "Thus, MPTP-exposed mice in this work ideally exhibited PD peripheral neuropathy, indicating that p-α-syn aggregated in peripheral nerves was possibly involved in TLR2/ NF-κB pathway." (PMID 34642321, 2021). "Toll-like receptors (TLR-1, TLR-2, and TLR-4) and the transient receptor potential family of ion channels (TRPV1 and TRPV4) have been discovered, demonstrating their active role in chemotherapy-induced peripheral neuropathy." (PMID 35956877, 2022).
respiratory disease (2 papers, 2016 to 2024). "Next, complementary analyses identified nine DMGs (LTA, STAT3, IKBKG, IRAK1, NOD2, TLR2, TNFRSF1A, and IKBKB) that might be involved in the immune response of XJB cattle infected with respiratory diseases." (PMID 38732144, 2024).
brain disease (1 paper, 2022). "Several other innate immune PRRs, such as TLR2, TLR4 and TLR9, have been implicated in the pathogenesis of bacterial, and specifically pneumococcal, brain disease, but in most cases in isolated cell culture conditions." (PMID 36028511, 2022).
gynecologic tumor (1 paper, 2022). "Some of the differential NRGs are unique to a particular gynecologic tumor, such as BCL2L11 and OTULIN in CESC, MAP3K7 in OV, TLR2 in UCS." (PMID 36357839, 2022).
retinopathies (1 paper, 2024). "To investigate the involvement of TLR2 in the protective effects of BoNT/A in retinopathies, we assessed Tlr2 mRNA expression in OIR retinas." (PMID 38922557, 2024). "We found that Tlr2 retinal expression increased during OIR which was suppressed by BoNT/A treatment, implying potential involvement of TLR2 in the protective effects of BoNT/A in retinopathies." (PMID 38922557, 2024).
vasculopathy (1 paper, 2020). "Patients with IIM have a differential pool of monocyte subsets with an enhanced expression of TLR2 and TLR4, which correlates with disease activity and distinctive clinical features including dysphagia, ILD, vasculopathy, and pro-inflammatory cytokines." (PMID 32164729, 2020).
TLR2 also shares sentences with these, for which no sentence is quoted: Allergy (20 papers); chronic periodontitis (20); acute myocardial infarction (5); aorta (5); apical periodontitis (5); Chronic Lymphocytic Leukemia (4); colon (4); eczema (4); Lewy body disease (4); oesophageal adenocarcinoma (4); systemic inflammatory response syndrome (4); acute-on-chronic liver failure (3); adenoma (3); cholestasis (3); endocarditis (3); follicular lymphoma (3); Parkinson (3); toxoplasmosis (3); vitiligo (3); Airway obstruction (2); allergic conjunctivitis (2); amoebiasis (2); autism (2); Burkholderia Infections (2); cardiac arrhythmias (2); chronic rhinosinusitis (2); corneal ulcer (2); cryptosporidiosis (2); duodenal ulcer (2); enterocolitis (2).
A further 181 diseases each share a sentence with TLR2 in 2 papers or fewer.